FOSL1 (FOS like 1, AP-1 transcription factor subunit)
Diseases named in the same sentence as FOSL1 in open-access papers (continued):
Sharing a sentence is not in itself a finding about the gene and the disease.
tumor (continued). "Notably, TFs such as TP63, FOSL1, and JUND were enriched in tumor-specific enhancer and super-enhancer domains, indicating their crucial role in tumorigenesis." (PMID 41323280, 2025). "The expression of FOSL1 is abnormal in many types of tumors, and it is upregulated in many tumors; however, its functions and content are not the same in different tumor types." (PMID 40821785, 2025). "This study compared the expression levels of miR-4516, Wnt 8B, FZD2, DVL3, FOSL1, CDK1, CDK2, CCNA1, and CCNB1 in primary LUAD tumor tissue with those in normal lung tissue using data from The Cancer Genome Atlas (TCGA) database to assess the consistency of our findings with the human sample." (PMID 38930863, 2024). "However, they significantly differed in terms of marker genes (AKR1C1, FOSL1, LIF, and THAP2 vs. WNT5A, GREM1, TNC, and MMP1), tissue origins (normal vs. tumor), and organ preferences." (PMID 38744958, 2024). "Key differentially expressed genes included PTGS2 (pro/antitumor), FOSL1, TNFRSF9, IL1B, DIO2, and PHLDA1 (antitumor), along with under-expressed genes with pro-tumor effects that may inhibit proliferation." (PMID 39409923, 2024). "Importantly, we functionally validated that FOSL1 and HNF4A cooperatively bind to a subset of tumor-specific hypoDMRs." (PMID 37620896, 2023). "The results showed that knocking down the expression of CEBPD and FOSL1 significantly reduced cells' invasive ability under hypoxic conditions, implying an important role of CEBPD and FOSL1 in hypoxia-induced tumor invasion." (PMID 37441593, 2023). "Mutations of the remaining two FOS genes, FOS Like 1 (FOSL1) and FOS Like 2 (FOSL2), have not been demonstrated in human tumours to date." (PMID 36426824, 2023). "Given the finding that c-FOS also transactivates FOSL1 expression and functions as an oncogene to promote tumor cell growth, it is not surprising that overexpression of c-FOS promotes EMT and accelerates tumor development and progression." (PMID 37353480, 2023). "Although beyond the scope of this work, it is tempting to speculate that FOSL1-mediated CEBPA depletion and reduced CEBPA-FOS/JUN interaction work in concert to promote tumor aggressiveness." (PMID 36631623, 2023). "Previous reports indicated that both FOSL1 and TCF7L2 had tumor suppressor activity." (PMID 34976185, 2022). "Conversely, average tumour volume of KRAS wild-type cells with FOSL1 inhibition did not change compared to the control group." (PMID 28220783, 2017). "The identification of FOSL1 through a cross-tumours approach including LAC, PDAC, CRC, CCA and MM suggested that it could be relevant in other KRAS-driven tumours." (PMID 28220783, 2017). "FOSL1 expression was plotted for each tumor stage identified within the data set, ignoring absent calls." (PMID 27220889, 2016). "Notably, these studies provided the rationale for combinatorial approaches involving either inhibition of DDR1 and Notch signaling or inhibition of the FOSL1 target AURKA and MEK, both of which blocked tumor initiation and progression as well as induced tumor regression." (PMID 29455666, 2018). "Furthermore, we established that FOSL1 positively regulates global m6A methyltransferase activity in a PRMT1-dependent manner, influencing the expression and function of key RNA methyltransferase METTL3 and its target transcripts involved in DDR and tumor progression." (PMID 41423530, 2025). "Moreover, higher FOSL1 levels may indicate the presence of metastases since specimens taken from patients with metastases in the liver and the lymph nodes exhibit more intense staining for FOSL1 than the tumor samples taken from the patients that do not have metastases." (PMID 35163444, 2022). "FOSL1 immunostaining was negative in 12/15 cases, whereas 3/15 (FTS5, FTS11, FTS12) showed equivocal weak nuclear immunoreactivity (1+) with a minor population of tumour cells demonstrating stronger (2+/3+) positivity." (PMID 36426824, 2023).
tumor (continued). "Despite FOSL1 stabilization in tumor cells that express constitutively activated RAS and RAF mostly depends on ERK-induced phosphorylation, high levels of phosphorylated FOSL1 can be observed even if the cells do not express constitutively active mutant forms of RAS or RAF." (PMID 35163444, 2022).
cancer (185 papers, 2006 to 2026). A tumor composed of atypical neoplastic, often pleomorphic cells that invade other tissues. "Extensive research has implicated FOSL1 as a critical regulator in various pathologies, particularly in cancer, where it governs tumorigenicity, proliferation, and metastasis." (PMID 41446762, 2025). "Secondly, aggressive forms of cancer are often associated with tumors that have higher levels of FOSL1." (PMID 38791400, 2024). "FOSL1 holds promise as a prognostic tool, as tumors with increased FOSL1 levels are often associated with aggressive cancer forms." (PMID 38791400, 2024). "FOSL1 gene, mapped in the 11q13, has been found to be a potential diagnostic marker and drug target for a variety of cancers." (PMID 37642779, 2023). "High FOSL1 expression, has been shown to be associated with a lower survival rate, indicating that quercetin can reduce cancer cell proliferation by reducing FOSL1 expression." (PMID 37298797, 2023). "Aberrant expression of FOSL1 has been linked to cancer stem cells and clonal selection of resistant phenotypes in cancer." (PMID 38038975, 2023). "Since FOSL1 is associated with most malignant forms of cancer and is often considered a poor prognostic factor for the outcome, it makes FOSL1 an attractive target for anticancer therapy." (PMID 35163444, 2022). "Stat3 and Tcf/Lef elements mediate cancer-associated FOSL1 induction in response to the IL6 and Wnt-beta-catenin pathways, respectively." (PMID 35326630, 2022). "The exact mechanism underlying the modulatory function of FOSL1 in cancer-related cell signaling, oncogene transcription, and cancer-specific chromatin structure forming DNA-loop requires further extensive investigation." (PMID 34722266, 2021). "MYC and FOSL1 have previously been shown to be the two main effector targets that are downregulated due to BETi treatment in various cancers including LAC, with MYC reexpression being linked to multiple resistance mechanisms." (PMID 33712563, 2021). "Second, tumors with higher FOSL1 levels are frequently associated with aggressive forms of cancer." (PMID 35163444, 2022). "To assess whether high expression levels of α6-integrin and FOSL1 may underlie K-Ras-driven human cancer progression, we performed an analysis of human cancer cell lines whose K-Ras mutation status has been documented." (PMID 28604746, 2017). "In glioma, FOSL1 can promote the transcription of miR-27a-5p and miR-221-3p by binding to the promoter region of genes, thus reducing the sensitivity of cancer cells to radiotherapy." (PMID 40821785, 2025). "We focused on the mutual relationship and potential molecular mechanisms between ncRNAs and FOSL1 during cancer development." (PMID 40821785, 2025). "Given the association of FOSL1 with elevated ERK1/2 activity and cancer cell invasion, we conducted gain-of-function assays with phosphomimetic mutants of FOSL1 and RELA." (PMID 40634284, 2025). "In other words, the ALKBH5-NEAT1-miR-378b-FOSL1 axis plays important roles in the development of cancer." (PMID 40821785, 2025). "In general, miRNAs act as upstream regulators of FOSL1 and play a role in inhibiting cancers, whereas downstream miRNAs promote the development of tumors." (PMID 40821785, 2025). "GSEA identified that the EMT, mammary stem cell, cancer stemness, and FOSL1 target gene sets’ expression levels were all significantly inhibited by knockdown of CYTOR in SCC1 and HN6 cells." (PMID 38032139, 2024). "FOSL1 reprograms differentiated cancer cells into stem-like cells by regulating four stemness-related transcription factors." (PMID 39227950, 2024). "Several studies reported the involvement of lncRNAs such as HOTAIR, AGAP2-AS1, LINC01503, and HOXA11-AS1 in the regulation of FOSL1 in cancer." (PMID 38791400, 2024). "Targeting FOSL1 has a strong inhibitory effect on the formation and spread of specific types of cancers." (PMID 38791400, 2024).
cancer (continued). "FOSL1 is identified as a crucial controller of invasion and metastatic dissemination, making it a potential target for therapeutic treatment in cancer patients." (PMID 38791400, 2024). "FOSL1 is upregulated in numerous malignancies, including GBM, and is implicated in cancer occurrence and development." (PMID 39227950, 2024). "SNAI2 has been demonstrated as a key target gene of FOSL1‐SEs to maintain cancer stemness and promote metastatic properties of HNSCC." (PMID 38032139, 2024). "The risk of developing oral squamous cell carcinoma (OSCC) is influenced by the transcription factors c-Jun and FOSL1, which also play a significant role in the cancer’s progression." (PMID 38791400, 2024). "Remarkably, FOSL1 (in PAAD and LUAD) and MYBL2 (in PAAD and BRCA) consistently showed associations with worse survival across multiple cancer types." (PMID 39393173, 2024). "Bosutinib sensitizes cancer cell lines to 5′-fluorouracil and gemcitabine by disrupting the Src-FOSL1 axis, resulting in decreased expression of mucins (MUC4 and MUC5AC)." (PMID 38791400, 2024). "It has been reported that the downregulation of miRNAs can result in increased expression of FOSL1 in various cancers." (PMID 38791400, 2024). "In summary, targeting FOSL1 has emerged as a potential strategy for overcoming drug resistance in cancer." (PMID 38791400, 2024). "Depletion of CYTOR leads to the disruption of FOSL1‐dependent SEs, which results in the inactivation of cancer stemness and pro‐metastatic genes." (PMID 38032139, 2024). "Among these, genes positively associated with mitogenic activities and cancer progression include FGF5, FOSL1, and FST (endcoding follistatin that belongs to the TGF-β superfamily)." (PMID 38612755, 2024). "FOSL1 protein is localized in the nucleus and cytoplasm and plays an essential role in cancer cell proliferation, invasion/metastasis, epithelial-to-mesenchymal transition (EMT), and antitumor immunity." (PMID 37642779, 2023). "Targeted RNA sequencing, performed on FFPE‐derived cDNA using TruSight® RNA Pan‐Cancer Panel, confirmed the FOSL1 breakpoint at the transcript level, which was further corroborated by strong nuclear immunoreactivity for FOSL1." (PMID 36426824, 2023). "Of these genes, we focused on FOSL1, which is involved in the therapeutic effect of ADSCs and the survival and proliferation of cancer stem cells." (PMID 36672268, 2023). "Among the genes that were particularly upregulated by SS, PRSS3, PAR2, and FOSL1 played important roles in cell invasion and cancer metastasis." (PMID 37395651, 2023). "Collectively, we can conclude that PRSS3, PAR2, and FOSL1 play important roles in the invasiveness and metastasis of cancer cells and that SS strengthens the metastatic ability of circulating cancer cells by upregulating these three genes." (PMID 37395651, 2023). "It has been reported that FOSL1 knockdown in cancer cells reduces their viability, and our findings represent the first time that FOSL1 was shown to be involved in ADSC survival." (PMID 36672268, 2023). "To elucidate the mechanisms through which SS upregulates PRSS3, PAR2, and FOSL1 to promote cell invasion and cancer metastasis, we first examined the kinases that were reported to modulate the activity and expression of AP‐1." (PMID 37395651, 2023). "This site is involved in the epithelial-mesenchymal transition (EMT) of cancer cells requiring a stable and intensive FOSL1 expression (see." (PMID 35163444, 2022). "FOSL1, a key component of the Activating protein-1 (AP-1) transcriptional complex, plays an important role in cancer cell migration, invasion, and proliferation." (PMID 36185257, 2022). "FOSL1 expression can be inhibited in cancer cells by several strategies, either irreversibly by gene editing, or reversibly by directly or indirectly targeting the Fra-1 mRNA." (PMID 35326630, 2022).
cancer (continued). "FOSL1 was initially found to be highly expressed in many cancer cells and was defined as a proto-oncogene, which was located at locus 11q13.1 and encoded a mature mRNA with a length of 1.7kb." (PMID 36032067, 2022). "For instance, the neoplastic cells of the advanced TNBC and atypical malignant tumors usually exhibit moderate-to-strong nuclear staining for FOSL1." (PMID 35163444, 2022). "In this case, the cytoplasmic FOSL1, presumably, is needed to activate the biosynthesis of phospholipids, which are required for the migrating cancer cells to support their rapid membrane biogenesis." (PMID 35163444, 2022). "Meanwhile, seven common genes, FOSL1, S100A9, CXCL12, ID2, PRS6KA3, AREG, and DUSP6, have been used as the target biomarkers and even the diagnostic tools in cancer therapy." (PMID 34490085, 2021). "Taken together, we identified a SE associated with the MIR21 gene driven by FOSL1 in HNSCC, which uncovers a novel mechanism underlying miR-21-5p regulation in cancer." (PMID 33937067, 2021). "Fos-like antigen-1 (FOSL1), belonging to the activator protein-1 transcription factor, has been suggested to be a potential biomarker of various human cancers." (PMID 32199129, 2020). "FOSL1 is also regulated by miRNA-34, a microRNA with a key role in cancer stemness, metastasis and chemo-resistance." (PMID 31438567, 2019). "As for FOSL1, the enrichment degree of its targets in the cell proliferation term is significantly different between normal and cancer cell lines." (PMID 30598101, 2018). "In this case, aging hypomethylated dmCpG sites tended to display a more marked enrichment of most of the cancer hypomethylation factors and, additionally, revealed the presence of other family‐ or function‐related proteins, like FOSL1/2, MAFF, MAFK, and STAT3." (PMID 29504244, 2018). "FOSL1 is a known proto-oncogene over-expressed in a variety of human cancers and plays important roles in oncogenesis in various malignancies." (PMID 29416636, 2018). "Here we report the identification of a common transcriptional signature across mutant KRAS cancers of distinct tissue origin that includes the transcription factor FOSL1." (PMID 28220783, 2017). "The enrichment of the super-enhancer markers exceeded that of known cancer-associated super-enhancers within the CCND2 and FOSL1 gene loci." (PMID 27624132, 2016). "FOSL1 is upregulated in several solid cancers, and is becoming a new target for cancer intervention." (PMID 18827820, 2008). "Here, using a SMARCA4-deficient LUAD cellular model, we show that SMARCA4 overexpression reorganizes enhancer landscapes and establishes a cooperative transcriptional network involving FOSL1, thereby promoting cancer cell proliferation and tumorigenic phenotypes." (PMID 42010258, 2026). "In addition, we further explored the potential clinical applications of the FOSL1-ncRNA system in cancer treatment, providing a theoretical basis for the study of FOSL1 and/or ncRNA-related molecular markers or targeted therapies." (PMID 40821785, 2025). "Consequently, we posited that our study substantiates, at least in part, the role of PMAIP1 in regulating the cancer progression of FTC via modulation of the Wnt3/FOSL1 pathway." (PMID 39944827, 2025). "In addition, we further explored the potential clinical application of the FOSL1-ncRNA system in cancer treatment, which provides a theoretical basis for research on molecular markers or targeted therapies related to FOSL1 and/or ncRNA." (PMID 40821785, 2025). "In esophageal carcinoma, the expression of the lncRNA AGAP2-AS1 increases, and AGAP2-AS1 can bind to miR-195-5p, resulting in a reduction in the content of FOSL1, a target gene of miR-195-5p, which then promotes the invasion and metastasis of cancer or inhibits apoptosis." (PMID 40821785, 2025).
cancer (continued). "However, more studies have shown that ncRNAs can regulate the expression and activity of FOSL1, thereby affecting the occurrence and development of tumors, which indicates that ncRNAs can be regulators of FOSL1 in cancer." (PMID 40821785, 2025). "This raised the question of whether PMAIP1 exerts a pro-cancer effect on FTC by regulating FOSL1 downstream of Wnt." (PMID 39944827, 2025). "The findings suggest that FOSL1 has a role in promoting cancer growth via AKT and enhancing cancer cell migration through JNK/c-Jun, identifying FOSL1 as a significant integrator of JNK and AKT signaling pathways, and a promising therapeutic target for treating cSCC and HNSCC." (PMID 38791400, 2024). "In summary, FOSL1 is emerging as a key regulator of CSCs in several cancer types." (PMID 38791400, 2024). "FOSL1 has also been shown to play a role in cancer stemness." (PMID 38791400, 2024). "Notably, all of these genes, such as TGFA, HB-EGF, EPHA2, IL8, MAP4K4, EMP1, DUSP6, as well as FOSL1, have an impact on signaling pathways that are recognized to play a significant role in the development of cancer." (PMID 38791400, 2024). "The effects of FOSL1 on apoptosis are contradictory in different types of cancer." (PMID 38791400, 2024). "Furthermore, BRD4 recruits Mediators and NF-κB p65 to form SEs at TP63, MET, FOSL1, and triggers transcription of cancer stemness genes and pro-metastatic genes in HNSCC." (PMID 39090713, 2024). "We also used a lung orthotopic model that was established in our previous study to investigate the importance of PRSS3, PAR2, and FOSL1 in the spontaneous metastasis of cancer cells by injecting A‐SSP6 cells transfected with shRNAs into the right lungs of NOD/SCID mice." (PMID 37395651, 2023). "Among them, we focused on FOSL1 in ADSCs because its expression has been shown to effectively protect against cartilage damage in Knee OA and because it is involved in the regulation of cell proliferation and survival in cancer stem cells." (PMID 36672268, 2023). "Although FOSL1 is highly expressed in most tumors and promotes malignant progression in malignant tumor 70, 71, but it may be at the core of T cell differentiation." (PMID 37215984, 2023). "In addition to transcriptional induction, the cancer-associated FRA-1 overexpression depends on the downregulation of the oncosuppressor miRNAs, which target the FOSL1 transcript." (PMID 37176013, 2023). "Speaking of cancer, we have to mention the decisive role of FOSL1 in EMT." (PMID 35163444, 2022). "Some authors report the cytoplasmic staining for FOSL1 in cancer cells." (PMID 35163444, 2022). "In addition, FOSL1 is involved in the progression of malignant tumours (oesophageal cancer, lung cancer, etc.)." (PMID 35484574, 2022). "Moreover, prefabricated viral particles deprived of their virulent factors will deliver specific sh-RNA to the cancer cells and produce a stable biological effect, i.e., silencing FOSL1 will be permanent." (PMID 35163444, 2022). "However, several options that involve unconventional mechanisms can be used to suppress and destabilize FOSL1 in cancer cells." (PMID 35163444, 2022). "Since transcription factor-mediated gene transcription depends on both its accessibility to cognate binding sites and its abundance, the authors determined gene expression of JUN and FOS family members and found overexpression of FOS, FOSB, and FOSL1 in the cancer." (PMID 34722266, 2021). "On the contrary, MYC and FOSL1 are restricted to cancer cells." (PMID 31438567, 2019). "Some of the transcription factors that were specifically expressed in OS-DW cells were ATF6, CDX2, FOSL1, PRDX3, FZD6, MYNN, TRAF1 which are known to regulate pathways implicated in cancers like, Wnt/Hedgehog/Notch signaling, MAPK signaling, Apoptosis and mTOR signaling." (PMID 31690262, 2019). "Moreover, chip-PCR analysis showed that STAT3 bind directly the FOSL1 gene promoter in cancer cell lines stimulated with IL6." (PMID 31438567, 2019).